IL18 (interleukin 18)
Diseases named in the same sentence as IL18 in open-access papers (continued):
Sharing a sentence is not in itself a finding about the gene and the disease.
Sepsis (continued). "The in vitro models of sepsis were successfully established via stimulating HUVEC and macrophages by LPS for 24 hours, which showed pyroptosis of HUVECs and macrophages with the release of proinflammatory factors IL-1β and IL-18." (PMID 32851082, 2020). "IL-1β and IL-18, the downstream cytokines secreted upon inflammasome activation, were determined in serum samples to further confirm the role of ASC-speck+ leukocytes in sepsis patients." (PMID 33613537, 2020). "However, the production of IL-18 is increased by lipopolysaccharide-stimulated NLRP3 inflammasome activation, indicating that IL-18 levels are increased in patients with sepsis." (PMID 32381117, 2020). "Thus, in the AOSD group, FGF-2, GM-CSF, IL-17, IL-18, and VEGF form interrelated networks, whereas in the sepsis group, IFN-γ, TNF-α, IL-8, IL-10, and IL-18 form interrelated networks." (PMID 32381117, 2020). "We observed elevation of the circulating IL18 in this CLP model in septic groups at all experimental points, indicating involvement in organ failure, since it is believed that high levels of IL18 are harmful in sepsis." (PMID 30850654, 2019). "Previous studies from our laboratory have demonstrated that caspase-1 does induce apoptosis during murine models of sepsis and that the apoptotic function is independent of its IL-1β and IL-18 processing function." (PMID 24643116, 2014). "It has been shown that the production of IFN-γ in response to IL-2 and IL-12 in combination (with or without IL-18) is altered in patients who undergo elective surgery and severely impaired in patients with sepsis." (PMID 23098236, 2012). "Lastly, we found that injecting LPS in Il18−/−, Ifng−/− and Il1b−/− mice treated with TNF-neutralizing antibodies abrogated the cellular effects validated above in all cases but lung granulocytes, suggesting that other pathways are likely at play for specific processes triggered by sepsis." (PMID 38191855, 2024). "In sepsis, the mitogen-activated protein kinase (MAPK) pathway is consistently activated in conjunction with the NF-κB pathway, either independently or cooperatively stimulating the secretion of downstream inflammatory factors such as COX-2, TNF-α, IL-1β, IL-18, IL-6, and iNOS." (PMID 39267971, 2024). "In addition, pneumonia-induced sepsis patients showed a markedly enhanced expression of IL-1β and IL-18 from plasma in comparison to pneumonia patients without sepsis and healthy people." (PMID 36923408, 2023). "Our result showed a considerable decrease in NLRP3, GSDMD-N, IL-18 protein expression, and serum IL-1β levels in the AFC and ASC groups compared to the ANC group, indicating that FMT and SCFAs can suppress cell pyroptosis and have a protective function in sepsis." (PMID 36713461, 2022). "The elevated secretion of IL-1β and IL-18, and expression pattern of HMBOX1, NF-κB (cytoplasm), nuclear NF-κB, NLRP3, caspase-1, and GSDMD-N were all reversed by overexpression of HMBOX1, showing that sepsis-exos and miR-885-5p mimic had similar effects on AC16 cells." (PMID 35345489, 2022). "Moreover, IL-10 levels were positively correlated with ferritin (ρ = 0.22, p = 0.047) and IL-18 (ρ = 0.33, p = 0.002) in the HBD + DIC subset but not in sepsis controls (ferritin: ρ = 0.06, p = 0.57; IL-18: ρ = 0.16, p = 0.167)." (PMID 35190900, 2022). "In addition to IL-18 TNF also represents a key mediator of sepsis and sepsis-induced organ injury." (PMID 35054259, 2021). "There may be no magic target to cure sepsis, and a combined approach could be more beneficial than targeting a single molecule, as shown for IL‐1 and IL‐18 in murine sepsis, IL‐1 and TNF in a rat model, or CD14 and factor XIa in rabbits." (PMID 32176432, 2020). "Multivariate classification followed by logistic regression analysis revealed that measurement of both FGF-2 and IL-18 could distinguish AOSD from sepsis with high accuracy (cutoff value for FGF-2 = 36 pg/mL; IL-18 = 543 pg/mL, sensitivity 100%, specificity 72.2%, accuracy 93.8%)." (PMID 32381117, 2020).
Sepsis (continued). "Moreover, for a model rat carrying sepsis, an MCT diet could significantly reduce the expression levels of pro-inflammatory cytokines and chemokines (TNF-α, IL-18, macrophage inflammatory protein-2, and MCP-1) in the ileum and Peyer’s patches." (PMID 31182969, 2019). "In addition to mediating renal disease, the IL-1/ IL-18 axis may also be responsible for development of CKD itself and its related complications, including vascular calcification and sepsis." (PMID 24450291, 2014). "First, patients with sepsis were selected for this exploratory study on the basis of interleukin-18 levels as well as based on having concurrent ARDS or not, which may limit external generalizability, as may the incidentally high proportion of participants with comorbid malignancy in this cohort." (PMID 35710638, 2022). "Finally, IL-1ra also blocks the effects of IL-18 which similarly modulates synaptic plasticity in the hippocampus; therefore, the role of IL-18 during the acute phase of sepsis may not have been eliminated from our study." (PMID 33643027, 2021). "Therefore, we studied the occurrence of pyroptosis and autophagy as well as the release of IL-1β and IL-18 after LPS stimulation of HUVECs and macrophages with RAPA, in order to understand whether the latter can be used in the earliest stages of sepsis to block inflammatory cytokine storm." (PMID 32851082, 2020). "While the interaction between TNF and IL-18 had not been reported to our knowledge, TNF plus IFN-γ38–41 or IL-1β42–44 worsen the outcome of sepsis and other inflammatory disorders in vivo." (PMID 38191855, 2024). "In pediatric critically ill populations, IL-18 levels were significantly elevated early in those without sepsis and AKI, but not in those with sepsis." (PMID 19082634, 2009). "A longitudinal study of extremely low birth weight (<1,000 g) measured cytokines at days 1, 3, 14, and 21 after birth and found that IFN-γ, IL-10, IL-18, TGF-β, and TNF-α levels differed among infants who developed fungal or bacterial LOS compared with those who never developed sepsis." (PMID 38312920, 2024). "In our study, IL-18 levels were not correlated with elevated LIGHT levels in either bacterial or viral sepsis, suggesting independent effects of LIGHT and IL-18 in sepsis, rendering a combination therapy with neutralizing antibodies to LIGHT and IL18 a feasible choice." (PMID 35203474, 2022). "In another study of a small cohort of sepsis, severe sepsis and shock patient admitted to ICU, the levels of IL-6, IL-8 and IL-18 resulted higher in non-survivors compared to survivors, although following multivariable logistic regression analysis only IL-18 remained related to mortality." (PMID 36189302, 2022). "Also, we did not observe significant changes in IL-1β and IL-18 levels between wild-type and Casp1−/− mice administered a high dose of HNP-1 after sepsis onset." (PMID 35935811, 2022).
Obesity (217 papers, 2007 to 2026). Accumulation of substantial excess body fat. "Obesity is linked to an increase in inflammatory cytokines, such as interleukin-6 (IL-6), IL-18, and tumor necrosis factor alpha (TNF-α), which are believed to play a role in HS and AC." (PMID 40969999, 2025). "On the other hand, we observed some differences in serum IFN-γ and IL-18 levels, both of which have been associated with obesity-induced adipose tissue inflammation." (PMID 40486661, 2025). "IL-18 levels were found to be elevated in diabetic nephropathy and have been linked to obesity, insulin resistance, hypertension, and dyslipidemia." (PMID 39273664, 2024). "Their substantial contributions, particularly in highlighting the consequences of IL‐18 deficiency and leading to heightened phagocytosis, obesity, and insulin resistance, hold significant and far‐reaching implications for IL‐18 research." (PMID 39188114, 2024). "We found increased levels of CCL5 in patients with obesity and obesity-associated T2D, with also higher levels of IL-6 and the ratio IL-18/IL-18BP." (PMID 38315242, 2024). "IL-18 is a pro-inflammatory cytokine that is associated with obesity, insulin resistance, hypertension, dyslipidaemia, and cardiovascular disease." (PMID 39064738, 2024). "Another study conducted on Korean women with obesity demonstrated that the–607 C/A polymorphism of IL-18 was related to higher BMI values." (PMID 39275140, 2024). "In the present study, IL-18 was the only NLRP3 protein studied which was associated with obesity status, but it was only predictive of SF-12 physical scores at 6-months and RPQ scores at 2-weeks in the severe obesity model." (PMID 38702410, 2024). "We find little evidence of differences across race/ethnicity, although inflammatory cytokine signaling was increased in black male β cells via IL18, a cytokine implicated in diabetes, obesity, and metabolic syndrome." (PMID 39567827, 2024). "Among the inflammatory mediators characterizing metabolic inflammation, interleukin 18 (IL-18) has been consistently associated with obesity and insulin resistance." (PMID 37049621, 2023). "In line, co-housing with Il18- or Asc-deficient mice led to increased steatosis and obesity in WT animals and antibiotic treatment reduced disease severity in Asc-deficient mice." (PMID 37239938, 2023). "Using mice models, they demonstrated that loss of Nlrp1 decreased IL-18 levels, lipolysis, and led to obesity and metabolic syndrome." (PMID 37819510, 2023). "Considering the importance of IL-1β and IL-18 in obesity-associated NASH and, consequently, in HCC progression, their therapeutic exploration appears to be promising for the management of this lethal cancer." (PMID 36289606, 2022). "A non-causal relation thus was previously suggested with PCOS and IL-18 levels because they both were linked to obesity as a confounding factor." (PMID 35263047, 2022). "Yet, IL18 deficiency in mice led to hyperphagia, obesity, insulin resistance, and decreased energy expenditure." (PMID 36482059, 2022). "Among the different inflammatory markers analyzed in the present study, IL-18 has been associated with increased cardiovascular risk, obesity, and insulin resistance." (PMID 36551255, 2022). "Considering the critical crosstalk between obesity, NASH, and HCC, this review will present the connections of IL-1β and IL-18 from obesity-associated NASH with HCC and will discuss approaches to using these cytokines as therapeutic targets against HCC." (PMID 36289606, 2022). "At the same time, clinical observations have implicated IL-18 in various metabolic diseases including obesity, type 1 (T1D) and type 2 (T2D) diabetes, and nonalcoholic fatty liver disease (NAFLD)/nonalcoholic steatohepatitis (NASH)." (PMID 36313762, 2022). "In mice and humans, obesity was associated with increased IL-18 levels in WAT, which contribute to systemic concentrations." (PMID 36313762, 2022).
Obesity (continued). "Of note, deficiency of IL-18 in mice leads to obesity and insulin resistance, largely due to hyperphagia." (PMID 36065376, 2022). "IL-18 is associated with obesity, atherosclerosis, insulin resistance/glucose intolerance, cardiovascular disease and multi-organ dysfunction." (PMID 36013509, 2022). "The initial study suggested that primary hyperphagia and resulting obesity were the cause of steatosis in IL-18-/- mice." (PMID 36313762, 2022). "On the contrary, studies performed on IL18-deficient mice proved that these developed late onset obesity and insulin resistance reversible after IL18 administration." (PMID 34207683, 2021). "Carriage of rs1946518 T at 2KB upstream of IL18 has been implicated in obesity in various populations." (PMID 34834553, 2021). "Obesity is associated with chronic adipose tissue inflammation, which is characterized by elevation of inflammatory cytokines, such as IL-18, TNF-α, and other adipokines released from adipose tissues." (PMID 32917958, 2020). "The following variables were significantly associated with the IL‐18 concentration at three out of the four occasions during follow‐up: male sex, obesity, diabetes and biomarkers of renal function (cystatin C), and inflammation (WBC, CRP‐hs, GDF‐15, Il‐10)." (PMID 31596518, 2019). "Inflammation plays a fundamental role in the pathophysiology of obesity, and pro-inflammatory cytokines IL-1β and IL-18 have already been linked to this metabolic disorder." (PMID 31998283, 2019). "In contrast, IL-18 has a neutral or beneficial role in triggering obesity-associated metabolic diseases (4.3.2)." (PMID 30717382, 2019). "Mice deficient for IL-18 or IL-18 receptor are susceptible to obesity and to develop glucose intolerance and IR32,33." (PMID 31554824, 2019). "Obesity is known to cause low-grade chronic inflammation, and elevated IL-18 levels have been found in obese and type 2 diabetics." (PMID 31835423, 2019). "IL-18-deficient mice spontaneously developed obesity and insulin resistance when fed a normal chow diet." (PMID 30717382, 2019). "Obesity and obesity-associated insulin resistance have been also associated with increased circulating IL-18 levels." (PMID 30619282, 2018). "Previous studies have reported that IL-18-deficient mice developed hyperphagia, obesity and insulin resistance." (PMID 30453990, 2018). "Despite these observations, other studies have implicated a protective function for inflammasome-activated IL-18 in obesity and the metabolic syndrome." (PMID 29515457, 2018). "Recently, IL-18 production from the NLRP1 inflammasome has been associated to the prevention of obesity and metabolic syndrome." (PMID 30619282, 2018). "Despite unequivocal evidences causally link IL-1β to the development of obesity-associated comorbities, IL-18, also activated by caspase-1, has been shown to ameliorate the development of obesity and insulin resistance." (PMID 30619282, 2018). "Susceptibility disorders for AD, including obesity, type-2 diabetes, cardiovascular diseases and metabolic syndrome have been linked to increases in the proinflammatory cytokine, IL-18, which also regulates multiple AD related proteins." (PMID 28531131, 2017). "Increased IL-18 levels, linked to MetS, obesity, cardiovascular diseases, T2DM, depression and stress, can have multiple impacts on neurons, with similarities in these conditions to those detected in AD." (PMID 28531131, 2017). "IL‐18R and IL‐18 mRNA/protein expression in obesity was associated with HOMA‐IR only in non‐diabetics." (PMID 28508444, 2017). "In regard with metabolic syndrome, IL‐18 is associated with obesity, insulin resistance, hypertension, atherosclerotic lesions, dyslipidemia, and cardiovascular disease." (PMID 28508444, 2017). "To confirm that increased activin levels in pancreatitis are independent of leptin deficiency, we used a complementary IL-12 + IL-18 induced model of necrotizing AP based on a high fat diet leading to diet-induced obesity (DIO)." (PMID 28986573, 2017).
Obesity (continued). "For example, some studies have shown that IL-18 cytokine is closely associated with insulin resistance and metabolic syndrome, including high blood pressure, hyperlipidemia, diabetes mellitus, obesity, and hypertension." (PMID 28042549, 2017). "The adipose tissue IL‐18R/IL‐18 expression is enhanced in obesity which associates with proinflammatory gene signature and insulin resistance in these individuals." (PMID 28508444, 2017). "IL-18 is generally considered a proinflammatory cytokine, associated with obesity and insulin resistance." (PMID 26788518, 2016). "Circulating levels of interleukin (IL)-18 appear to be associated with a number of micro- and macrovascular comorbidities of obesity and T2DM." (PMID 26930607, 2016). "The role of IL-18 during development of obesity seems to be ambivalent as it has been shown that deficiency of either IL-18 or IL-18 receptor triggers obesity and hyperinsulinemia in mice and that treatment with recombinant IL-18 reversed these effects." (PMID 26788518, 2016). "Elevated IL-18 has been detected in several risk conditions for AD, including obesity, type-II diabetes, and cardiovascular diseases as well as in stress." (PMID 22898493, 2012). "In order to investigate the possible roles of the SNPs from the IL-18 gene promoter region (−137 G/C and −607 C/A) in the development of obesity, the genetic polymorphisms of obese subjects were evaluated." (PMID 22531046, 2012). "Knockout of IL-18 or its receptor results in obesity and insulin resistance, and fasting IL-18 levels are reduced following weight loss in humans." (PMID 22474579, 2012). "The purpose of this study is to evaluate the relationship between IL-18 gene polymorphisms (−137 G/C and −607 C/A) and obesity." (PMID 22531046, 2012). "The present study is the first approach in exploring the role of the IL-18 gene promoter polymorphism in the etiology of obesity in the Korean population." (PMID 22531046, 2012). "Deficiencies of IL-18 in mice (Il18−/−) led to the exhibition of late- onset obesity and insulin resistance." (PMID 22531046, 2012). "We investigated variation within the IL18 gene and its association with measures of obesity and the metabolic syndrome." (PMID 20227263, 2011). "Variation in IL18 has been associated with IL-18 levels and measures of obesity in men with T2D and subjects with advanced coronary heart disease and with insulin sensitivity in the Catanzaro Metabolic Risk (CATAMERI) study in Italy." (PMID 20227263, 2011). "In agreement with our findings, earlier studies showed Il-18-deficient mice developed obesity, insulin resistance, and hyperglycemia." (PMID 20307313, 2010). "This was the first research exploring the role of IL-18 gene promoter polymorphism in the etiology of PCOS and its relation with IR and obesity.But we study only two site of IL-18 gene polymorphism, we will continue our work in the future." (PMID 20964873, 2010). "In a large cross sectional study, elevated IL-18 levels were associated with increasing number of components also after adjustment for insulin resistance, obesity, IL-6 and CRP." (PMID 20331890, 2010). "IL-18 has in several studies been associated with obesity, insulin resistance, hypertension and dyslipidemia." (PMID 20331890, 2010). "In humans, the plasmatic concentration of IL18 is an interesting predictor of the risk of myocardial infarction, artherosclerosis and metabolic syndrome observed in obesity." (PMID 19664222, 2009). "Notably, elevated IL-18 levels observed in individuals with obesity are associated with IL-18 resistance and decrease following weight loss." (PMID 39496966, 2025). "Pathways beyond NLRP3 inflammasome activation may contribute to IL-18 production, which has also been directly linked to obesity in previous studies." (PMID 40004007, 2025).